PCSK5 (proprotein convertase subtilisin/kexin type 5)
Description:
Serine endoprotease that processes various proproteins by cleavage at paired basic amino acids, recognizing the RXXX[KR]R consensus motif. Likely functions in the constitutive and regulated secretory pathways. Plays an essential role in pregnancy establishment by proteolytic activation of a number of important factors such as BMP2, CALD1 and alpha-integrins.
Synonyms: PC5; PC6; SPC6; PC6A
Tractability: Small molecule: a high-quality ligand is known. Antibody: its Gene Ontology location is reachable by antibodies, with high confidence; UniProt places it where antibodies can reach, with medium confidence; UniProt predicts a signal peptide or a membrane-spanning region. PROTAC: ubiquitination databases record sites on it; a small molecule that binds it is known.
Target class: Enzyme; Serine protease S8B subfamily; Serine protease SB clan; Protease; Serine protease
Gene: Protein-coding gene on chromosome 9 (75,890,644 to 76,362,975, forward strand). Ensembl gene ENSG00000099139.
Subcellular location: Secreted (Isoform PC6A); Endomembrane system (Isoform PC6B)
Subcellular location (Human Protein Atlas): Golgi apparatus; Predicted to be secreted
Pathways (Reactome):
Signal Transduction: NGF processing
Transport of small molecules: Assembly of active LPL and LIPC lipase complexes
Gene Ontology:
Molecular function: endopeptidase activity; endopeptidase inhibitor activity; peptidase activity; protein binding; serine-type endopeptidase activity; peptide binding; serine-type peptidase activity
Biological process: anterior/posterior pattern specification; cholesterol homeostasis; embryonic digestive tract development; embryonic skeletal system development; kidney development; negative regulation of low-density lipoprotein particle receptor catabolic process; peptide biosynthetic process; peptide hormone processing; protein processing; renin secretion into blood stream; viral life cycle; cell-cell signaling; cytokine precursor processing; embryo implantation; heart development; limb morphogenesis; plasma lipoprotein particle remodeling; respiratory tube development; proteolysis; secretion by cell
Cellular component: Golgi apparatus; extracellular region; Golgi lumen; Golgi membrane; trans-Golgi network; endomembrane system
Genetic constraint (gnomAD): Loss-of-function variants: 87 observed, 143.54 expected, observed/expected ratio (o/e) 0.61, 90% interval 0.51 to 0.72. The upper end of that interval is the gene's LOEUF score, 0.72, which puts it in group 2 of 6, group 1 being the genes least tolerant of losing a copy. Missense variants: 1,635 observed, 1,943.2 expected, observed/expected ratio (o/e) 0.84, 90% interval 0.81 to 0.88. Synonymous variants: 654 observed, 716.58 expected, observed/expected ratio (o/e) 0.91, 90% interval 0.86 to 0.97.
Gene-disease validity (ClinGen):
ClinGen rates the evidence that PCSK5 causes each of these diseases.
syndromic congenital heart disease (autosomal dominant): Disputed. Congenital heart disease with co-occurrence of other extracardiac congenital anomalies, or well characterized genetic conditions.
Homologues: Orthologues: chimpanzee PCSK5 (97% identical), macaque PCSK5 (96% identical), pig PCSK5 (87% identical), rabbit PCSK5 (86% identical), dog PCSK5 (86% identical), guinea pig PCSK5 (81% identical), rat Pcsk5 (81% identical), mouse Pcsk5 (81% identical), tropical clawed frog pcsk5 (63% identical), zebrafish pcsk5b (25% identical). Paralogues in human: PCSK6 (27% identical), FURIN (20% identical), PCSK4 (17% identical), PCSK1 (16% identical), PCSK7 (15% identical), PCSK2 (15% identical), MBTPS1 (10% identical), TPP2 (9% identical), PCSK9 (6% identical).
Diseases named in the same sentence as PCSK5 in open-access papers:
PCSK5 is named in the same sentence as 45 diseases in open-access papers, as found by Europe PMC text mining. Sharing a sentence is not in itself a finding about the gene and the disease. The quoted sentences say what the papers report.
chronic kidney disease (3 papers, 2022 to 2024). Impairment of the renal function secondary to chronic kidney damage persisting for three or more months. "Recently, PCSK5 has been shown to be involved in the generation of urinary peptides associated with the progression of chronic kidney disease." (PMID 37474514, 2023). "Whether ApoExos and PCSK5 contribute to the transition from acute kidney injury to chronic kidney disease will be addressed of future studies." (PMID 37474514, 2023).
diabetes (3 papers, 2011 to 2024). "Moreover, PCSK5 might be a potential target to lower LDL levels and valuable for the ANGPTL4 (angiopoietin like 4)-mediated target therapy of diabetes and metabolic syndrome." (PMID 38483771, 2024).
Obesity (3 papers, 2013 to 2024). Accumulation of substantial excess body fat. "Here, we found that some DMR genes are obesity genes or related to the former which have been studied by genomic and genome-wide association study (GWAS) methods, for example, FTO, PCSK5, PCSK6, NTRK2, ABCC4, TXNIP and RPS6KA2." (PMID 31637123, 2019). "In conclusion, this study demonstrates upregulation of furin-like PCSKs (furin and PCSK5) for the first time and, furthermore, an imbalance of furin and its inhibitor serpinB8 in obesity." (PMID 23936445, 2013). "Therefore, the Pcsk5 might be a potential obesity candidate gene to be explored in the future." (PMID 38483771, 2024).
Alzheimer disease (2 papers, 2011 to 2012). A progressive, neurodegenerative disease characterized by loss of function and death of nerve cells in several areas of the brain leading to loss of cognitive function such as memory and language. "As such, PCSK5 is involved in neurodevelopment and has been associated with a decrease in ventricular volume in a case-control cohort collected for Alzheimer’s disease and Mild Cognitive Impairment." (PMID 23049896, 2012).
atherosclerosis (2 papers, 2021 to 2022). A disease characterized by the build-up of fatty material and calcium deposition in the arterial wall resulting in partial or complete occlusion of the arterial lumen. "Moreover, furin and PCSK5 can enhance the inflammatory response in atherosclerosis." (PMID 34576019, 2021). "In atherosclerosis, we found that the expression of FURIN, PCSK5 and MBTPS1 was significantly lower in carotid plaques vs. normal artery controls, while PCSK6 and PCSK7 were increased." (PMID 36188622, 2022).
breast carcinoma (2 papers, 2010 to 2022). "Similarly, for early breast cancer, the best three k-gene discriminators are {GPR109B, PCOLCE2, PCSK5}, {PCSK5+COL10A1, FERMT2+SPINT2, MAOA+IGJ}, {COL1A1+PCSK5+TF, GPX3+COL1A1+SPINT2, GPX3+FAP+TMEM97}, and {RRM2+COL1A1+GPR109B+IGJ, RRM2+COL1A1+GPR109B+IGJ, RRM2+COL1A1+GPR109B+SPINT2}, respectively." (PMID 21060876, 2010).
endometriosis (2 papers, 2023 to 2025). The growth of functional endometrial tissue in anatomic sites outside the uterine body. "Comparative analysis of WES data from RPL patients and healthy controls identified polymorphisms in the proprotein convertase subtilisin/kexin type 5 (PCSK5) and mucin 2 (MUC2) genes, both previously reported in association with endometriosis." (PMID 40724834, 2025). "Numerous studies based on cell or animal models have confirmed that FOS1, EPHX1, and PCSK5 have significant effects on the occurrence and development of endometriosis, which is consistent with the results of this study." (PMID 38098472, 2023). "Although the PCSK5 and MUC2 genes have previously been implicated in endometriosis, their involvement in pregnancy loss has not been well characterized." (PMID 40724834, 2025).
inflammatory skin disease (2 papers, 2022 to 2024). Inflammatory skin disorders covers a broad category that includes many conditions ranging in severity, from mild itching to grave medical health complications These disorders are common in people of all ages and races. "PCSK5 is upregulated in liver fibrosis and may also be a biomarker reflecting local disease activity in inflammatory skin disease." (PMID 38397136, 2024).
triple-negative breast carcinoma (2 papers, 2018 to 2020). An invasive breast carcinoma which is negative for expression of estrogen receptor (ER), progesterone receptor (PR), and human epidermal growth factor receptor 2 (HER2). "PCSK5 (proprotein convertase subtilisin/kexin type 5) was found to be dysregulated in different subtypes of triple-negative breast cancer (TNBC)." (PMID 30243023, 2018). "In triple-negative breast cancer (TNBC), a lack of PCSK5 could lead to the bioactivity of growth differentiation factor (GDF11) as a tumor-suppressor." (PMID 32647495, 2020).
autism spectrum disorder (1 paper, 2021). A spectrum of developmental disorders that includes autism, and Asperger syndrome. "Other important genes identified by gene-based GWASs include neural adhesion molecules CNTN4 (p = 3.88e-9) on chr3p26.3-p26.2 which has been linked to autism spectrum disorders, PCSK5(p = 2.88e-11) on chr9q21.13, and CDH13 (p = 4.19e-8) on chr16q23.3) and TMEM132 (p = 2.18e-8) on chr17q12." (PMID 34868193, 2021).
caudal regression syndrome (1 paper, 2021). "Since these phenotypic features resembled those seen in VATER/VACTERL association (OMIM% 192350), caudal regression syndrome (OMIM #600145) and CS, the authors coined the term Vcc for this Pcsk5 mutation." (PMID 33836786, 2021). "This treatment inhibited Pcsk5 and Gdf11 expression in the hindgut at E12 and E18 and also resulted in a phenotype resembling caudal regression syndrome and CS." (PMID 33836786, 2021).
diabetic nephropathy (1 paper, 2022). "However, the single-cell transcriptomic analysis revealed that PCSK5 was differentially expressed in early human diabetic nephropathy." (PMID 35045102, 2022).
intestinal tumors (1 paper, 2017). "The PCSK5 gene (also known as PC5 or PC6) has been reported to be systematically down-regulated in intestinal tumors of the knockout mouse model and human." (PMID 28249600, 2017).
liver disease (1 paper, 2024). "A subsequent genome-wide association study (GWAS) identified shared single-nucleotide polymorphisms (SNPs) in the genes AR, EDIL3, MACROD2, PCSK5, RUNX1T1, TENM4, and ZEB2 between PN and liver disease from the FinnGen cohort." (PMID 38397136, 2024).
malaria (1 paper, 2021). Malaria is a serious and sometimes fatal disease caused by a parasite that commonly infects a certain type of mosquito which feeds on humans. "Genes with top scores encode for different malaria relevant functions such as regulation of inflammation (CSMD1), neural adhesion (CNTN4, PCSK5, CDH13, TMEM132), vascular epithelial development (FLT4), and protein kinases (PTPRT, PRKG1)." (PMID 34868193, 2021).
pancreatic cancer (1 paper, 2022). "While Furin has been reported to promote pancreatic cancer growth, there is no study on Pcsk5 or the efficacy of CMK in PDAC to date." (PMID 36970723, 2022).
pancreatic tumor (1 paper, 2022). "Unbiased RNA-seq analyses comparing pancreatic tumor cell lines derived from the pancreatic tumors of the PKC versus the N4−/−PKC mice led to the identification of Pcsk5 as a potential downstream mediator of Notch4 signaling." (PMID 36970723, 2022). "RNA-sequencing analysis of pancreatic tumor cell lines derived from the PKC and N4−/−PKC GEMMs revealed that 408 genes were differentially expressed (FDR < 0.05) and Pcsk5 is a potential downstream effector of the Notch4 signaling pathway (P < 0.001)." (PMID 36970723, 2022).
peripheral arterial disease (1 paper, 2022). A disorder of the arteries supplying the upper and lower extremity and the visceral organs. "PCSK5 mRNA expression in plaques showed a positive link to peripheral arterial disease and a negative correlation with lipid rich necrotic core volume." (PMID 36188622, 2022).
cancer (10 papers, 2016 to 2024). A tumor composed of atypical neoplastic, often pleomorphic cells that invade other tissues. "Several reports revealed that PCSK5 is involved in the development of embryos, whereas only few evidences have confirmed that PCSK5 is associated with cancer." (PMID 35646694, 2022). "CMK is a general PCs inhibitor (Pcsk5 included), and has been successfully used for certain cancer types." (PMID 36970723, 2022). "Functional protein domains were frequently altered, especially by CASEs affecting cancer drivers, such as PCSK5." (PMID 31695792, 2019). "Specifically, NEFH, hepatitis A virus cellular receptor 1 (HAVCR1, 5q33.2), interferon, alpha-inducible protein 27 (IFI27, 14q32), PCSK5, and the arylsulfatase D gene (ARSD, Xp22.3) have been implicated in a variety of cancers." (PMID 28249600, 2017). "Three additional predicted cancer driver mutations (EPHA7, MAP3K12, and PCSK5) were identified that were acquired during the transformation of non‐malignant MCF10A cells to malignant DCIS.com cells that could also be implicated in the cell‐context dependency of SOX11 in promoting invasion." (PMID 28707729, 2017). "Another compound is inhibin β-A (INHBA), which induces EMT and accelerates the motility of cancer cells by activating the TGF-β and proprotein convertase subtilisin/kexin type 5 (PCSK5)." (PMID 39120301, 2024).
tumor (7 papers, 2013 to 2025). "Among these, 3 genes including TIMM17B, NTSE and PCSK5 were significantly down‐regulated in tumour tissues compared to normal controls, which is consistent with prior sequencing results." (PMID 41354645, 2025). "Taking these previous reports into accounts, we hypothesize that Notch4-meidated Pcsk5 regulation may involve cross-talk with the activin/TGFβ signaling pathways during pancreatic tumorigenesis, thus affect tumor burden and survival." (PMID 36970723, 2022). "Together, these results suggest that the loss of Notch4 can lead to downregulated expression of Pcsk5 in PanIN and PDAC lesions, and may have contributed to the reduced tumor burdens and improved survival in the N4−/−PKC mice." (PMID 36970723, 2022). "PCSK5 expression is a predictor for tumor response to the EGFR tyrosine kinase inhibitor erlotinib." (PMID 31101650, 2019). "Hence an alternative hypothesis would be that the inactivation of Notch4 can induce inhibition of Pcsk5 expression, resulting in impaired tumor angiogenesis and, consequently, reduced tumor burden and increased survival." (PMID 36970723, 2022). "The results indicated that AIFM3, HSH2D, and PTPN6 were significantly up-regulated, while DCHS1, PTGIS, FLRT2, PCSK5, and CLSTN2 were significantly down-regulated in tumor samples compared with normal samples." (PMID 34512722, 2021). "Moreover, Pcsk5 inhibition has been shown to result in inhibition of VEGF-C, a key factor in angiogenesis and tumor nourishment and development." (PMID 36970723, 2022).
infection (2 papers, 2021 to 2024). The state of being infected such as from the introduction of a foreign agent such as serum, vaccine, antigenic substance or organism. "Similarly, the activation of genes such as Serping1, Sparc, Pcsk5, Fgf7, and Cyp7b1 indicated the temporal activation of cell migration and immune suppression during infection." (PMID 38767331, 2024).
PCSK5 also shares sentences with these, for which no sentence is quoted: Cognitive impairment (2 papers); acute myocardial infarction (1); adenocarcinoma (1); Anal atresia (1); autism (1); bipolar disorder (1); colon cancer (1); Currarino syndromes (1); depression (1); endometrial adenocarcinoma (1); Esophageal atresia (1); gout (1); Hyperglycemia (1); infertile (1); kidney (1); liver fibrosis (1); lung carcinoma (1); metabolic syndrome (1); microdeletion syndrome (1); Parkinson disease (1); renal agenesis (1); schizophrenia (1); Tracheoesophageal fistula (1); viral infection (1).